NDUFAF6 (NADH:ubiquinone oxidoreductase complex assembly factor 6)
Description:
Involved in the assembly of mitochondrial NADH:ubiquinone oxidoreductase complex (complex I) at early stages. May play a role in the biogenesis of complex I subunit MT-ND1.
Synonyms: C8orf38; lncREST; MGC40214; FRTS5; MC1DN17
Tractability: PROTAC: ubiquitination databases record sites on it; its protein half-life has been measured.
Gene: Protein-coding gene on chromosome 8 (94,895,533 to 95,116,455, forward strand). Ensembl gene ENSG00000156170.
Subcellular location: Mitochondrion inner membrane (Isoform 1); Cytoplasm (Isoform 2); Nucleus
Pathways (Reactome):
Metabolism: Complex I biogenesis
Gene Ontology:
Biological process: mitochondrial respiratory chain complex I assembly
Cellular component: mitochondrial inner membrane; mitochondrion; cytoplasm; nucleus
Genetic constraint (gnomAD): Loss-of-function variants: 37 observed, 31.07 expected, observed/expected ratio (o/e) 1.19, 90% interval 0.92 to 1.57. The synonymous counts are far from expectation, so gnomAD's model fits this gene poorly and the ratio says little. Missense variants: 414 observed, 368.54 expected, observed/expected ratio (o/e) 1.12, 90% interval 1.04 to 1.22. Synonymous variants: 174 observed, 132.3 expected, observed/expected ratio (o/e) 1.32, 90% interval 1.16 to 1.49.
Gene-disease validity (ClinGen):
ClinGen rates the evidence that NDUFAF6 causes each of these diseases.
Leigh syndrome (autosomal recessive): Definitive. A progressive neurological disease defined by specific neuropathological features associating brainstem and basal ganglia lesions.
mitochondrial disease (autosomal recessive): Definitive.
Homologues: Orthologues: chimpanzee NDUFAF6 (99% identical), macaque NDUFAF6 (95% identical), dog NDUFAF6 (88% identical), guinea pig NDUFAF6 (86% identical), rabbit NDUFAF6 (85% identical), pig NDUFAF6 (83% identical), mouse Ndufaf6 (82% identical), rat Ndufaf6 (70% identical), zebrafish ndufaf6 (61% identical), tropical clawed frog NDUFAF6 (55% identical), Drosophila melanogaster sicily (37% identical), Caenorhabditis elegans B0334.5 (30% identical). Paralogues in human: MMGT1 (10% identical).
Diseases named in the same sentence as NDUFAF6 in open-access papers:
NDUFAF6 is named in the same sentence as 32 diseases in open-access papers, as found by Europe PMC text mining. Sharing a sentence is not in itself a finding about the gene and the disease. The quoted sentences say what the papers report.
Leigh syndrome (8 papers, 2016 to 2026). "Biallelic mutations in NDUFAF6-a key assembly factor of complex I-cause autosomal recessive Leigh syndrome, specifically NDUFAF6-related Leigh syndrome, also designated as mitochondrial complex I deficiency, nuclear type 17 (MC1DN17; OMIM 618239)." (PMID 41982415, 2026). "Pathogenic variants in NDUFAF6 have been increasingly recognized as a cause of mitochondrial disease, particularly Leigh syndrome, a severe neurodegenerative disorder characterized by bilateral symmetrical lesions in the central nervous system." (PMID 41924699, 2026). "Previous reported cases of pathogenic variants in NDUFAF6 present with a range of symptoms, including Leigh syndrome and the Acadian variant of Fanconi syndrome 5 (proximal renal tubular dysfunction) (FRTS5, MIM 618913)." (PMID 40400026, 2025). "Here, we present a rare case of a child who developed Leigh syndrome due to pathogenic variants of NDUFAF6, which encodes an assembly factor of complex I, a respiratory chain subunit." (PMID 35664867, 2022). "For example, the human NDUFAF6 gene has been implicated in Leigh syndrome, a severe neurometabolic disorder that arises early in life." (PMID 26935103, 2016). "Loss-of-function mutations of sicily, the fly ortholog of NDUFAF6, result in progressive neurodegeneration, impairment of mitochondrial complex I function and increased production of reactive oxygen species, symptoms that are all seen in individuals with Leigh syndrome." (PMID 26935103, 2016).
breast carcinoma (3 papers, 2022 to 2024). "In summary, the differential expression of NDUFAF6 in breast cancer is associated with various biological processes and pathways, especially its connection with the NRF2 pathway." (PMID 38459583, 2024). "These comprehensive analyses firmly establish the significant association between NDUFAF6 expression in breast cancer and several crucial clinical pathological parameters, strongly suggesting NDUFAF6 as a potential molecular biomarker in breast cancer patient's diagnosis, prognosis, and treatment." (PMID 38459583, 2024). "In the mouse model of breast cancer xenografts, we observed that sh-NDUFAF6 significantly inhibited the protein level of PD-L1 in the tumor compared to sh-NC." (PMID 38459583, 2024). "Through Spearman correlation testing, we explored the relationship between immune cell enrichment in breast cancer tissues and the expression patterns of NDUFAF6." (PMID 38459583, 2024). "NDUFAF6 expression was an independent predictor of breast cancer outcomes in both univariate and multivariate analyses." (PMID 38459583, 2024). "We successfully established a breast cancer cell xenograft mouse model by subcutaneously inoculating MCF-7 breast cancer cells with inhibited or overexpressed NDUFAF6." (PMID 38459583, 2024). "The mitochondrial protein NDUFAF6, previously studied in liver cancer, is now being investigated for its role in breast cancer." (PMID 38459583, 2024). "In order to investigate the impact of NDUFAF6 expression on the tumor microenvironment in breast cancer, we utilized the ssGSEA algorithm provided in the R package "GSVA"." (PMID 38459583, 2024). "Using logistic regression analysis, we further explored the relationship between NDUFAF6 expression and several adverse clinical features of breast cancer." (PMID 38459583, 2024). "A breast cancer cell xenograft mouse model was used to evaluate tumor growth, apoptosis, and NDUFAF6 expression." (PMID 38459583, 2024). "In conclusion, NDUFAF6 protein expression is significantly elevated in BC patients and breast cancer cell xenograft mice." (PMID 38459583, 2024). "To delve deeper into the role of NDUFAF6 in breast cancer progression, we conducted a series of in vivo experiments to reveal its potential regulatory mechanisms on breast cancer cell proliferation and apoptosis." (PMID 38459583, 2024). "This study aims to explore the expression and functional significance of NDUFAF6 in breast cancer using various databases and experimental models." (PMID 38459583, 2024). "Against this backdrop, we focused on studying the expression pattern of the NDUFAF6 gene in breast cancer, especially its relationship with key clinical pathological indicators." (PMID 38459583, 2024). "Against this backdrop, we delved into the role of NDUFAF6 in breast cancer using the Cancer Genome Atlas (TCGA) and Gene Expression Omnibus (GEO) databases." (PMID 38459583, 2024). "In vivo experiments further revealed that NDUFAF6 could promote PD-L1 expression in breast cancer cells by inhibiting the NRF2 signaling pathway." (PMID 38459583, 2024). "The study establishes NDUFAF6 as a potential prognostic biomarker in breast cancer." (PMID 38459583, 2024). "Overall, NDUFAF6 significantly promoted the proliferation of breast cancer MCF-7 cells in vivo." (PMID 38459583, 2024). "NDUFAF6 was found to be overexpressed in breast cancer patients and in the xenograft mouse model." (PMID 38459583, 2024). "Through in-depth mechanistic studies, we revealed that NDUFAF6 affects immune infiltration and tumor growth in BC by inhibiting the NRF2 signaling pathway, thereby promoting PD-L1 expression in breast cancer cells." (PMID 38459583, 2024). "In summary, the collaboration between NDUFAF6 and NRF2 promotes the expression of PD-L1 and tumor growth in breast cancer cells." (PMID 38459583, 2024).
breast carcinoma (continued). "This discovery provides additional evidence supporting the hypothesis of NDUFAF6 as a therapeutic target or predictive biomarker and offers new theoretical foundations and practical guidance for the diagnosis, treatment, and prognosis assessment of breast cancer." (PMID 38459583, 2024). "Therefore, we investigated the effect of NDUFAF6 on NRF2 and its potential role in PD-L1 expression and breast cancer cell growth." (PMID 38459583, 2024). "We analyzed breast cancer samples from The Cancer Genome Atlas (TCGA), Gene Expression Omnibus (GEO), and Human Protein Atlas (HPA) databases, supplemented with immunohistochemistry (IHC) staining to assess NDUFAF6 expression." (PMID 38459583, 2024). "Next, we evaluated the stromal, immune, and ESTIMATE scores in breast cancer using the ESTIMATE method, revealing a significant negative correlation with NDUFAF6 expression." (PMID 38459583, 2024).
Dystonia (2 papers, 2024 to 2025). An abnormally increased muscular tone that causes fixed abnormal postures. "Mutations in the NDUFA9 and NDUFAF6 genes, which are complex I assembly factors, have also been linked to dystonia." (PMID 37750949, 2024).
hepatocellular carcinoma (2 papers, 2023 to 2024). A malignant tumor that arises from hepatocytes. "NDUFAF6 has been suggested to be involved in the pathogenesis of hepatocellular carcinoma by controlling mitochondrial-mediated translational processes." (PMID 38459583, 2024). "Recently, NDUFAF6 was found to have significant prognostic potential in hepatocellular carcinoma." (PMID 38459583, 2024).
Coronary arteriosclerosis (1 paper, 2024). "Coronary arteriosclerosis shared 10 GWS genes with AD (BAG6, C6orf10, HLA-DQB1, HLA-DRA, HLA-DRB1, NDUFAF6, NME7, PLCG2, PRRC2A, and TRIB1), while myocardial infarction shared three genes with AD (HLA-DRA, PHB, and RP11-81K2.1)." (PMID 39201500, 2024).
parasitic infections (1 paper, 2024). "Further GSEA analysis revealed significant pathways between high and low NDUFAF6 expression groups, including Leishmania infection, parasitic infections, IL12 pathway, NRF2 pathway, allograft rejection, and viral myocarditis." (PMID 38459583, 2024).
prostate carcinoma (1 paper, 2024). A carcinoma that arises from epithelial cells of the prostate gland. "Previous research identified a novel genomic fusion event between NDUFAF6 and ARHGEF3 in prostate cancer." (PMID 38459583, 2024).
pulmonary fibrosis (1 paper, 2024). Chronic progressive interstitial lung disorder characterized by the replacement of the lung tissue by connective tissue, leading to progressive dyspnea, respiratory failure, or right heart failure. "Familial pulmonary fibrosis has been linked to mutations in genes on telomeres, including NDUFAF6." (PMID 38459583, 2024).
staphylococcus aureus infection (1 paper, 2024). An infectious process in which the bacteria Staphylococcus aureus is present. "Through GO and KEGG enrichment analyses, we found that NDUFAF6 is mainly associated with biological processes and pathways such as Staphylococcus aureus infection, antimicrobial humoral response, defense responses against gram-positive and gram-negative bacteria, and humoral immune response." (PMID 38459583, 2024).
vascular dementia (1 paper, 2022). A degenerative vascular disorder affecting the brain. "DGR350 had a heterozygous variant in NDUFAF6 (p.Ala92Val), a gene which was recently identified as a novel locus associated with AD in a meta-analysis focussing on AD and vascular dementia patients." (PMID 35699875, 2022).
cancer (5 papers, 2021 to 2024). A tumor composed of atypical neoplastic, often pleomorphic cells that invade other tissues. "Subsequently, we assessed the relationship between NDUFAF6 levels and the prognosis of cancer patients." (PMID 38459583, 2024). "The findings indicate that NDUFAF6 expression is significantly elevated in 23 types of cancers, including BC." (PMID 38459583, 2024). "It is worth noting that the expression of NDUFAF6 had a high discriminatory ability to distinguish cancer from healthy tissue, with an AUC value of 0.931." (PMID 38459583, 2024). "Using TCGA data, we initially assessed the expression pattern of NDUFAF6 across pan-cancers, specifically in BC." (PMID 38459583, 2024). "Additionally, clinical sample testing of BC samples was conducted; IHC analysis confirmed an elevated protein expression of NDUFAF6 compared to healthy tissues adjacent to malignant tumors." (PMID 38459583, 2024).
tumor (3 papers, 2023 to 2024). "Additionally, we analyzed the differential genomic alterations and functional networks associated with NDUFAF6 expression and its role in tumor immunity." (PMID 38459583, 2024). "The results showed that the expression pattern of NDUFAF6 negatively correlated with several anti-tumor immune cells, such as pDC cells and neutrophils, which play major roles in tumor suppression." (PMID 38459583, 2024). "Conversely, ov-NDUFAF6 significantly increased the protein level of PD-L1 in the tumor compared to ov-NC." (PMID 38459583, 2024). "Similarly, in 112 pairs of matched normal breast tissue and tumor tissue samples, the expression of NDUFAF6 was significantly increased in tumor tissue." (PMID 38459583, 2024). "As the figure shown, P300 was positively related to NDUFAF6 and OVOL1, and negatively related to tumor suppress gene IGFBP6." (PMID 37950222, 2023). "NDUFAF6 showed a negative correlation with anti-tumor immune cells like pDC cells and neutrophils, suggesting that NDUFAF6 might influence the TME, affecting BC progression and prognosis." (PMID 38459583, 2024).
mitochondrial disease (1 paper, 2026). "To date, this represents the largest reported cohort of patients with NDUFAF6-associated mitochondrial disease." (PMID 41924699, 2026). "To date, fewer than 50 patients with NDUFAF6-related mitochondrial disease have been reported, displaying a broad phenotypic spectrum ranging from early-onset neurodevelopmental regression to milder, more chronic presentations." (PMID 41924699, 2026).
NDUFAF6 also shares sentences with these, for which no sentence is quoted: Alzheimer disease (1 paper); behavioral disorders (1); cerebellar ataxia (1); cholestasis (1); Cockayne syndrome (1); Encephalomyopathies (1); exocrine pancreatic insufficiency (1); Fanconi syndrome (1); keratoconus (1); liver cancer (1); liver dysfunction (1); macrocytic anaemia (1); myocardial infarction (1); osteosarcoma (1); OXPHOS disease (1); renal tubular acidosis (1); retinal degeneration (1); viral myocarditis (1); xeroderma pigmentosum (1).